LINC00632 (long independently transcribed non-coding RNA 632)
Synonyms: ASINC; ARST; CDR1NAT; ciRS-7; CDR1as; MDHDH; BMOR; CDR1-AS
Gene: Long non-coding RNA gene on chromosome X (140,709,562 to 140,793,215, forward strand). Ensembl gene ENSG00000203930.
Diseases named in the same sentence as LINC00632 in open-access papers:
LINC00632 is named in the same sentence as 70 diseases in open-access papers, as found by Europe PMC text mining. Sharing a sentence is not in itself a finding about the gene and the disease. The quoted sentences say what the papers report.
melanoma (17 papers, 2019 to 2024). A malignant, usually aggressive tumor composed of atypical, neoplastic melanocytes. "LINC00632 was reported to be associated with several tumors including multiple myeloma cell drug resistance, and melanoma invasion and metastasis." (PMID 35372082, 2022). "For example, epigenetic silencing of LINC00632 could result in the CDR1as depletion, which promoted invasion in vitro and metastasis in vivo through a miR-7-independent, IGF2BP3-mediated mechanism in melanoma." (PMID 33505440, 2020).
glioma (14 papers, 2020 to 2025). A benign or malignant brain and spinal cord tumor that arises from glial cells (astrocytes, oligodendrocytes, ependymal cells). "To estimate the epidemiological value of MDHDH in glioma patients, we divided 776 patients from the TCGA glioma datasets into two groups according to the relative expression levels (cutoff value: 50%) of MDHDH (TCGA transcript annotation: LINC00632-005)." (PMID 36527092, 2022). "According to the TCGA database, LINC00632 is downregulated in the glioma tissues and glioma cell lines." (PMID 34099027, 2021). "The glioma patients with high expression level of LINC00632 are associated with better long-term and disease-free survivals, potentially suggesting a similar role of ARST in gliomagenesis." (PMID 34099027, 2021). "Moreover, low LINC00632 expression correlated with poor overall survival and disease-free survival in the glioma patients." (PMID 34099027, 2021). "LncRNAs AC091878.1 and RP11-108L7.15 identified as protective factors in the m5C LPS were found to be significantly higher in WHO Grade II tumors while LINC00632 and PAXIP.AS1 presented significantly higher expression in WHO Grade III gliomas." (PMID 35372082, 2022). "Five genes (KIF5C, LINC00632, B4GALNT3, HIF3A, and RAD51L3-RFFL) show significant differential expression between primary and recurrent tumors, with four having established functional roles in glioma pathobiology." (PMID 41356219, 2025). "We classified the 40,650 astrocytomas obtained by Seurat and named the seven subclusters according to the marker genes as C0 IGFBP7+ Glioma cells, C1 OLIG2+ Glioma cells, C2 LINC02283+ Glioma cells, C3 LINC00632+ Glioma cells, C4 MX1+ Glioma cells, C5 FOSB+ Glioma cells, and C6 DLL3+ Glioma cells." (PMID 39403379, 2024). "The identification of five genes (KIF5C, LINC00632, B4GALNT3, HIF3A, and RAD51L3-RFFL) with differential expression between primary and recurrent tumors provides critical insight into the molecular mechanisms driving recurrence, the key challenge in the management of IDH wild-type glioma." (PMID 41356219, 2025).
esophageal squamous cell carcinoma (10 papers, 2018 to 2025). Esophageal squamous cell carcinoma (ESCC) is a type of esophageal carcinoma (EC) that can affect any part of the esophagus, but is usually located in the upper or middle third. "CiRS-7 (CDR1as or CDR1NAT), a cancer suppressor derived from the lncRNA LINC00632 transcripts, is upregulated in osteosarcoma (OS) and esophageal squamous cell carcinoma (ESCC)." (PMID 32171304, 2020).
allergic rhinitis (1 paper, 2020). Inflammation of the nasal mucous membranes caused by an IgE-mediated response to external allergens. "Yue and colleagues found that linc00632 was down-regulated in nasal tissues of allergic rhinitis patients and inhibited IL-13 induced inflammatory cytokine and mucus production." (PMID 32637070, 2020).
retinal degeneration (1 paper, 2025). Degeneration of the retina. "Importantly, our RNA-seq and RT-qPCR data analysis revealed tissue-specific dysregulation of LINC00632 and CDR1as/ciRS-7, suggesting this is the most likely cause of retinal degeneration." (PMID 39892393, 2025).
Retinal dystrophy (1 paper, 2025). Retinal dystrophy is an abnormality of the retina associated with a hereditary process. "We describe a new genomic mechanism for retinal dystrophy, and our data support a convergent tissue-specific mechanism of altered regulation of LINC00632 and CDR1as/ciRS-7 as a consequence of the insertions within the palindrome on Xq27.1." (PMID 39892393, 2025). "Based on these findings, we reasoned that tissue-specific dysregulation of LINC00632 could represent a potential convergent mechanism for retinal dystrophy, prompting further experimental investigations to explore this hypothesis." (PMID 39892393, 2025). "However, if CDR1as/ciRS-7 transcription originates solely from the LINC00632 promoter within the SOX3 TAD, then we would expect it to be upregulated in our retinal dystrophy RO models, owing to the upregulation of the parental linear isoforms." (PMID 39892393, 2025).
LINC00632 also shares sentences with these, for which no sentence is quoted: tumor (70 papers); cancer (64); hepatocellular carcinoma (28); myocardial infarction (24); ovarian carcinoma (17); colorectal cancer (15); gastric cancer (12); Alzheimer disease (11); breast cancer (10); glioblastoma (8); bladder cancer (7); cholangiocarcinoma (6); diabetes (6); non-small cell lung carcinoma (6); Parkinson disease (6); colon cancer (5); lung cancer (5); cervical carcinoma (4); liver cancer (4); diabetic cardiomyopathy (3); laryngeal squamous cell carcinoma (3); lung adenocarcinoma (3); neuroblastoma (3); osteosarcoma (3); acute myocardial infarction (2); astrocytoma (2); behavioral disorders (2); cardiovascular diseases (2); chronic heart failure (2); colitis (2).
A further 34 diseases each share a sentence with LINC00632 in 2 papers or fewer.